RN7SKP223 (RN7SK pseudogene 223)
Gene: Miscellaneous RNA gene on chromosome 7 (138,091,254 to 138,091,315, forward strand). Ensembl gene ENSG00000222514.
Homologues: Paralogues in human: RN7SKP174 (89% identical), RN7SKP171 (85% identical), RN7SKP239 (85% identical), RN7SKP47 (85% identical), RN7SKP69 (85% identical), RN7SKP107 (84% identical), RN7SKP144 (84% identical), RN7SKP198 (84% identical), RN7SKP208 (84% identical), RN7SKP294 (84% identical), 7SK (82% identical), RN7SKP119 (82% identical), and 284 more.